KDM4C (lysine demethylase 4C)
Diseases named in the same sentence as KDM4C in open-access papers (continued):
Sharing a sentence is not in itself a finding about the gene and the disease.
lung carcinoma (continued). "We provide evidence that genetical or pharmacological inhibition of KDM4C impairs tumorigenesis and radioresistance in lung cancer in vitro and in vivo." (PMID 33558705, 2021). "Targeting of KDM4C with genetical or pharmacological inhibition significantly overcomes lung cancer radioresistance in vitro and in vivo." (PMID 33558705, 2021). "Deregulation of KDM4C, a H3K9me3 and H3K9me2 demethylase, has been identified in several solid tumors, such as esophageal squamous carcinoma, lung cancer, pancreas cancer, and breast cancer." (PMID 32908544, 2020). "In lung cancer, KDM4C expression is higher in adenocarcinoma than in squamous cell carcinoma." (PMID 37067993, 2023). "Our data reveal a crucial role for KDM4C in antitumor immunity in lung cancer and indicate that targeting KDM4C in combination with radioimmunotherapy might be a promising synergistic strategy in lung cancer." (PMID 35121645, 2022). "To test this hypothesis, we first targeted KDM4C genetically or pharmacologically in multiple human lung cancer cell lines and Lewis cells and detected a significant increase in the protein expression of CXCL10." (PMID 35121645, 2022). "In addition, we also showed the presence of an endogenous interaction between USP9X and KDM4C in lung cancer cells." (PMID 33558705, 2021). "In addition, we revealed that USP9X is involved in lung cancer progression and radioresistance in a KDM4C-dependent manner." (PMID 33558705, 2021). "Furthermore, we present evidence that genetical or pharmacological inhibition of KDM4C overcomes radioresistance in lung cancer by inactivating the TGF-β2/Smad/ATM signaling pathway." (PMID 33558705, 2021). "In addition, our data also showed that USP9X-depleted lung cancer cells exhibited increased olive tail moment and enhanced radiosensitivity, and these phenotypes were also partially rescued by re-expressing KDM4C." (PMID 33558705, 2021). "Moreover, we showed that there was a correlation between high expression of KDM4C and shorter overall survival in lung cancer patients by Kaplan–Meier survival analysis (P < 0.05)." (PMID 33558705, 2021). "More importantly, we uncover a novel role of KDM4C in promoting lung cancer radioresistance." (PMID 33558705, 2021). "Moreover, we also uncovered that USP9X preferentially upregulates the protein levels of KDM4C by preventing its ubiquitination in lung cancer." (PMID 33558705, 2021). "Importantly, we are the first to report that the deubiquitinase USP9X is responsible for the upregulation of KDM4C in lung cancer." (PMID 33558705, 2021). "Considering that KDM4C is substantially overexpressed in lung cancer tissues, we assumed that it might exert a tumorigenic effect in lung cancer." (PMID 33558705, 2021). "More importantly, we examined the synergistic effect of combining SD70, an epigenetic KDM4C-specific inhibitor, with RT and an anti-PD-L1 antibody and found that among the tested regimens, this triple therapy produced the best antitumor effects with tolerable toxicity in lung cancer." (PMID 35121645, 2022). "To further clarify the role of USP9X in lung cancer radioresistance and confirm whether this effect is dependent on KDM4C, we transfected exogenously expressed KDM4C into USP9X-depleted cells and found that TGF-β2, p-Smad2 and p-Smad3 protein levels were decreased when USP9X was knocked down." (PMID 33558705, 2021). "In addition, the functional results reveal that genetic deletion or pharmacological inhibition of KDM4C suppressed tumor growth in vitro and in vivo, further supporting our hypothesis that KDM4C acts as an oncoprotein in lung cancer." (PMID 33558705, 2021). "For instance, in lung cancer, USP9X drives tumor progression by stabilizing the oncoprotein lysine-specific demethylase 4C (KDM4C)." (PMID 41301681, 2025). "Previous research has shown that inhibiting KDM4C induces the transcription of Cxcl10, enhancing CD8+ T cell-mediated antitumor immune responses in lung cancer." (PMID 38622609, 2024).
lung carcinoma (continued). "A synergistic strategy combined with a lysine-specific demethylase 4 C (KDM4C) inhibitor plus radiotherapy and PD-L1 blockade has been identified with efficacy in lung cancer." (PMID 37635168, 2023). "We showed that ubiquitin-specific protease 9X (USP9X) mediates lysine-specific demethylase 4C (KDM4C) deubiquitination, which activates transforming growth factor-β2 (TGF-β2)/Smad/ATM signaling to promote radioresistance in lung cancer." (PMID 35875060, 2022). "More importantly, among the tested regimens, a triple therapy (the KDM4C-specific inhibitor SD70 plus RT and an anti-PD-L1 antibody) produced the best antitumor effect against lung cancer in vivo." (PMID 35121645, 2022). "More importantly, using ChIP-PCR, we revealed that H3K36me3 binding at the promoter region of CXCL10 was increased considerably after KDM4C inhibition, indicating that KDM4C directly regulates the transcriptional level of the CXCL10 gene in lung cancer." (PMID 35121645, 2022). "A C57BL/6 mouse tumor model was developed to evaluate the efficacy and safety of a triple therapy (the KDM4C-specific inhibitor SD70 plus RT and an anti-PD-L1 antibody) in lung cancer in vivo." (PMID 35121645, 2022). "Inhibition of KDM4C with shRNAs or SD70 treatment reduced the basal expression levels of TGF-β2, BMP2 and JUND while increasing the expression level of GDF11 in lung cancer cells." (PMID 33558705, 2021). "In summary, our study identifies the upstream modulator and downstream mediator of KDM4C and reveals that targeting KDM4C via blocking TGF-β2/Smad signaling impairs tumorigenesis and enhances radiosensitivity in lung cancer." (PMID 33558705, 2021). "KDM4C inhibition reduces the expression of TGF-β2 and decreased the protein levels of p-Smad2 and p-Smad3 in lung cancer cells." (PMID 33558705, 2021). "Here, we show that lysine-specific demethylase 4C (KDM4C) is overexpressed and correlated with poor prognosis in lung cancer patients." (PMID 33558705, 2021). "Consistently, a previous study has shown that KDM4C can increase cell migration and invasion via CUL4A in lung cancer." (PMID 32908544, 2020). "Given that USP9X co-localized with KDM4C and a significant positive correlation between the expression of USP9X and KDM4C in lung cancer tissues was observed, we conclude that USP9X overexpression may account for KDM4C upregulation in human lung cancer." (PMID 33558705, 2021). "Importantly, restoration of KDM4C partially rescued the reduced levels of TGF-β2, p-Smad2 and p-Smad3 in USP9X-depleted lung cancer cells, suggesting that USP9X silencing inhibits TGF-β2/Smad signaling in a KDM4C-dependent manner." (PMID 33558705, 2021). "Inhibition of KDM4C with SD70 can not only suppress cell growth in vitro and in vivo but also accelerate DNA damage and inhibit DNA repair, ultimately enhancing radiosensitivity in lung cancer." (PMID 33558705, 2021). "Therefore, we concluded that SD70-induced KDM4C inhibition increases the CXCL10 transcriptional level to mediate the increased intratumoral infiltration and activation of CD8+ T cells, which in turn enhances the efficacy of our triple therapy in lung cancer." (PMID 35121645, 2022). "Moreover, we uncover that KDM4C upregulates TGF-β2 expression by directly reducing H3K9me3 level at the TGF-β2 promoter and then activates Smad/ATM/Chk2 signaling to confer radioresistance in lung cancer." (PMID 33558705, 2021). "Thus, our findings demonstrate that USP9X-mediated KDM4C deubiquitination activates TGF-β2/Smad signaling to promote radioresistance, suggesting that targeting KDM4C may be a promising radiosensitization strategy in the treatment of lung cancer." (PMID 33558705, 2021). "To further evaluate the therapeutic potential of KDM4C inhibition, we used SD70, a selective competitive inhibitor of KMD4C, to block its catalytic domain without affecting its expression and tested its efficacy on lung cancer cell functions." (PMID 33558705, 2021).
acute myeloid leukemia (12 papers, 2014 to 2024). Acute myeloid leukemia (AML) is a group of neoplasms arising from precursor cells committed to the myeloid cell-line differentiation. "PRMT1 has already been proposed to be a potential epigenetic target in acute myeloid leukemia because it has been recognized to contribute to an aberrant epigenetic networks with KDM4C." (PMID 32517078, 2020). "show that PRMT1 is necessary but insufficient for acute myeloid leukemia induction by chimeric transcription factors, which also recruit KDM4C for epigenetic reprogramming." (PMID 26766589, 2016). "KDM4C activity is required for development of acute myeloid leukemia." (PMID 35654819, 2022). "In murine models of acute myeloid leukemia (AML) driven by MLL-rearrangements, genetic inactivation of all Kdm4 family members blunted leukemia development while inactivation of Kdm4c alone showed minor effects regarding proliferation of leukemic cells." (PMID 35654819, 2022). "In acute myeloid leukemia (AML), ALKBH5 was positively regulated by KDM4C and the high level of ALKBH5 increased the stability of AXL (AXL receptor tyrosine kinase), thus promoting leukemia stem cells." (PMID 36686788, 2022). "In addition, ALKBH5 is known to post-transcriptionally regulate TACC3 to promote tumorigenesis and cancer stem cell self-renewal in acute myeloid leukemia (AML), whereas the KDM4C-ALKBH5-AXL signaling axis participates in chromatin alterations in AML leukemia stem cells." (PMID 34491904, 2021).
esophageal squamous cell carcinoma (11 papers, 2012 to 2024). Esophageal squamous cell carcinoma (ESCC) is a type of esophageal carcinoma (EC) that can affect any part of the esophagus, but is usually located in the upper or middle third. "Specifically, KDM4C is upregulated in the tumor-initiating cells isolated from patient samples of esophageal squamous cell carcinoma, and caffeic acid treatment suppresses the demethylation activity of KDM4C." (PMID 36975603, 2023). "KDM4C, an oncogene that is frequently amplified in esophageal squamous cell carcinomas, is able to demethylate tri- and dimethylated lysine 9 on histone H3 and activates subsequent oncogenic pathways." (PMID 32908544, 2020).
leukemia (11 papers, 2016 to 2025). A malignant (clonal) hematologic disorder, involving hematopoietic stem cells and characterized by the presence of primitive or atypical myeloid or lymphoid cells in the bone marrow and the blood. "Chromatin remodeling complexes, including the BAF (BRG1/BRM-associated factor) complex and the histone demethylase KDM4C, are key regulators of gene expression in KMT2Ar leukemias." (PMID 39682203, 2024). "In leukemia stem cells (LSCs), KDM4C enhances ALKBH5 level by elevating chromatin accessibility at the ALKBH5 locus, diminishing H3K9me3 levels, and facilitating the binding of MYB and Pol II." (PMID 40186131, 2025). "Here, inactivation of the KDM4C-ALKBH5 axis resulted in reduced proliferation, impaired colony formation and loss of leukemia stem cells." (PMID 35654819, 2022). "in AML development revealed ALKBH5, affected by chromatin accessibility through KDM4C, is required in the maintenance of the leukaemia stem cell function by affecting the stability of AXL receptor tyrosine kinase (AXL) transcripts in an m6A‐dependent manner." (PMID 35340126, 2022). "A previous study revealed that combined activity of Kdm4a, Kdm4b, and Kdm4c is required for AML with a rearrangement of the mixed‐lineage leukemia gene (MLL‐AF9‐translocated AML) in vitro and in vivo, using Kdm4a−c triple knockout mice." (PMID 34938963, 2021). "Together, these results highlight an essential function of Kdm4c in leukemias driven by MLL fusions and MOZ-TIF2." (PMID 26766589, 2016). "Similar to Prmt1 in vivo knockdown data, the few leukemias from the mice that received Kdm4c-knockdown cells actually re-expressed high levels of Kdm4c and Hoxa9, indicating a strong growth disadvantage of Kdm4c knockdown leukemia cells." (PMID 26766589, 2016). "To further demonstrate the therapeutic potentials of targeting KDM4C in AML, we tested the leukemia inhibitory activity of a newly developed KDM4C inhibitor, SD70." (PMID 26766589, 2016). "Thus, we provided evidence that among the KDM4 family, KDM4A and KDM4C are the most efficient potential targets in leukemia treatment." (PMID 35836814, 2022). "We have shown that the small molecule compound SD49-7, which targets KDM4A and KDM4C, could inhibit leukemia progression." (PMID 35836814, 2022). "Taken together, compared to SD70, SD49-7 could efficiently inhibit KDM4A and KDM4C, resulting in leukemia suppression." (PMID 35836814, 2022). "Histone demethylases are known to play a role in regulating LSCs and targeting KDM4C by SD70 could inhibit leukemogenesis in a spontaneous leukemia mouse model." (PMID 35836814, 2022). "Furthermore, only simultaneous knockout of the demethylases Kdm4a, Kdm4b, and Kdm4c perturbed progression of MLL-AF9 translocated leukemias in mice." (PMID 34944554, 2021). "Other KDM4 family members (i.e., KDM4A, KDM4C, and KDM4D) were found to be expressed at lower and similar levels across the cytogenetic subgroups of AML including the mixed lineage leukemia gene‐associated leukemia (11q23/MLL) etc.." (PMID 34938963, 2021). "Similarly, inhibition of Kdm4c expression significantly delayed disease latency of MOZ-TIF2-induced leukemia (log-rank test p < 0.0001)." (PMID 26766589, 2016). "The discovery of the functional crosstalk between PRMT1 and KDM4C in the establishment of an oncogenic transcriptional program in leukemia provides important insights into the molecular functions and underlying mechanisms of these critical PMTs and KMDs in oncogenesis." (PMID 26766589, 2016). "In contrast to mice transplanted with control transduced MLL-GAS7 leukemic cells that all succumbed to leukemia within 6 weeks, Kdm4c knockdown in leukemic cells abolished their oncogenic activity, and all mice remained healthy even after 14 weeks of observation." (PMID 26766589, 2016).
leukemia (continued). "Together, these findings provide strong experimental and preclinical in vivo evidence demonstrating an efficient MLL leukemia suppression by pharmacological inhibition of KDM4C, laying the foundation for future clinical application of KDM4C inhibitors in human cancer treatments." (PMID 26766589, 2016). "This is also consistent with the finding that KDM4C is required for PRMT1-independent MLL leukemia." (PMID 26766589, 2016). "We also observed that SD49-7 showed stronger leukemia cell inhibition than SD70, which preferentially binds to KDM4C." (PMID 35836814, 2022). "shRNA-mediated knockdown of KDM4C in MLL-GAS7, MLL-AF9, and MOZ-TIF2 leukemia cell lines increased differentiation, cell cycle arrest, and apoptosis." (PMID 34944554, 2021). "As KDM4C binds to MLL N-terminus region, KDM4C is also required for leukaemia induced by other MLL fusions independent on PRMT1, suggesting a much broader function of KDM4C in maintaining aberrant epigenetic networks in MLL leukaemia." (PMID 27593928, 2017). "KDM4C has been reported to act as a regulator in AML 13, and inhibition of Kdm4c could inhibit leukemogenesis in a murine leukemia model." (PMID 35836814, 2022). "Depleting KDM4A and KDM4C by either shRNA or SD49-7 enhanced trimethylation of H3K9 occupying the promoter of MDM2 and activated p21CIP1 by decreasing MDM2 expression, inhibiting the stemness and proliferation, and activating apoptosis of leukemia cells." (PMID 35836814, 2022). "Multiple findings demonstrate a key role for KDM4C in MLL- and MOZ-TIF2-driven leukemia." (PMID 34944554, 2021). "Furthermore, treatment with the KDM4C inhibitor SD70 drastically reduced the leukemic burden and significantly extended disease latency in mice transplanted with MLL-AF9 leukemia cells." (PMID 34944554, 2021). "PRMT1 is necessary but not sufficient for leukemia induction by chimeric transcription factors, which also recruit KDM4C, for epigenetic reprogramming." (PMID 26766589, 2016). "Consistent with the data on mouse primary transformed cells, SD70 induced apoptosis, differentiation, and cell-cycle arrest accompanied with an increased level of H3K9me3 mark in MLL leukemia cell lines, suggesting a similar requirement of KDM4C activity in both human and mouse MLL leukemias." (PMID 26766589, 2016). "To investigate whether Kdm4c is also required for maintenance of leukemia in vivo, we transduced MLL fusions and MOZ-TIF2 leukemia cells harvested from primary leukemic mice with a scramble control or the Kdm4c shRNA prior to their transplantation into syngeneic mice for disease development." (PMID 26766589, 2016). "We found that the mRNA level of KDM4A was slightly decreased by SD49-7 in both THP-1 and MLL-AF9 leukemia cells, whereas it decreased KDM4A and KDM4C protein levels only in THP-1 cells, but not in MLL-AF9 leukemia cells." (PMID 35836814, 2022). "We demonstrated that KDM4A and KDM4C, but not KDM4B, regulated leukemia progression." (PMID 35836814, 2022).
colon cancer (10 papers, 2016 to 2025). "KDM4C inhibition by curcuminoids is an adjuvant therapy that can benefit colon cancer patients." (PMID 29619118, 2018). "Taken together, these data indicate that CRISPRoff effectively reduces the expression of KDM4C in various cell lines and this downregulation was maintained in HCT116 colon cancer cells." (PMID 40537846, 2025). "Recently, another demethylase KDM4C has also been shown to bind onto the JAG1 promoter to mediate β-catenin-dependent transcription of JAG1 and to maintain sphere-forming capacity in colon cancer cells." (PMID 27029061, 2016). "Curcuminoids, derivatives of curcumin, are favorable in reducing JMJD2C/KDM4C activity in vivo, and could be deployed in the treatment of colon cancer." (PMID 37218871, 2023).
colorectal cancer (10 papers, 2018 to 2025). A primary or metastatic malignant neoplasm that affects the colon or rectum.